BRCA1 (BRCA1 DNA repair associated)
Diseases named in the same sentence as BRCA1 in open-access papers (continued):
Sharing a sentence is not in itself a finding about the gene and the disease.
cancer (continued). "The silencing of BRCA1 and associated difference in susceptibility of HCC1937/wt BRCA1 to PB show that a mutated BRCT domain 2 at the C-terminus of BRCA1 plays an important role in mediating the specific activity of PB in BRCA1-defective cancers." (PMID 27229859, 2016). "Therefore, a multiplicative model of cancer risk for BRCA1 and BRCA2 is inconsistent with the current observations." (PMID 27836010, 2016). "There is also a discussion whether therapeutic radiation is associated with increased risk of induced cancers in BRCA1/2 heterozygotes." (PMID 27555886, 2016). "Because metformin has attracted interest as an antitumor agent in cancer prevention and treatment, we explored the possible impact of metformin treatment on metabolic rewiring induced by pathogenic mutation of a single BRCA1 allele." (PMID 27259235, 2016). "Interestingly, many BRCA1-mutated TNBC show characteristic patterns in CNAs leading to the classification of BRCA1-mutated cancers as BRCA1-like or non-BRCA1-like TNBC." (PMID 27213343, 2016). "It was reported that in BRCA1 deficient cancer cells, loss of 53BP1 leads to PARP inhibitor resistance, therefore we checked whether the loss of 53BP1 can also cause PARP inhibitor resistance in CtIP-depleted cells." (PMID 26713604, 2016). "However, it is not clear what would be the best marker that can be used for identifying CSCs in BRCA1 mutated cancers." (PMID 27229859, 2016). "Reduced BRCA1 mRNA expression levels were previously reported in BRCA1-associated cancer." (PMID 27534398, 2016). "High Ubc9 expression due to BRCA1 mutation may trigger an early growth and transformation advantage to normal breast and ovarian epithelial cells resulting in aggressive cancers." (PMID 28164176, 2016). "Clinical resequencing of a high‐risk cancer susceptibility gene such as BRCA1 (MIM #113705) or BRCA2 (MIM #600185) may reveal that a patient carries a clearly pathogenic sequence variant." (PMID 26913838, 2016). "Imbalance in Ubc9 levels due to BRCA1 mutation can tilt this balance resulting in cancer." (PMID 28164176, 2016). "Based on the data presented here, we envision that 53BP1 hypo-phosphorylation and the associated failure of RIF1 recruitment may emerge as novel indicators for PARPi resistance in BRCA1-deficient cancers." (PMID 27494840, 2016). "In addition,the use of inhibitors can exploit DNA repair defects in certain cancer cells.For example, the deficiency in homologous recombination in BRCA1/2-deficientcells makes them acutely sensitive to PARP inhibition." (PMID 27437145, 2016). "In another study, cancer risk reductions were in the order of 32 and 49 % among women with BRCA1 mutation who breastfed for at least one year (OR 0.68; 95 % CI 0.52–0.91; p = 0.008) and for two or more years (OR 0.51; 95 % CI 0.35–0.74; p = 0.0003), respectively." (PMID 27129401, 2016). "Therefore, we examined BRCA1 assemblies in cancer cell lines having a naturally mutated BRCT domain and known deficiencies in transcriptional activities." (PMID 27583302, 2016). "PARP inhibitors are used in cancer cells with mutated BRCA1 and BRCA2 proteins." (PMID 26973813, 2016). "Inhibition of PARP is an effective strategy for suppressing cancers with BRCA1 and BRCA2 mutations." (PMID 27147578, 2016). "Both of these mutations are likely to be deleterious variants in BRCA1-associated cancer." (PMID 27836010, 2016). "Compounds that interfere with early stages of cancer formation are particularly appropriate for mutation carriers and evidence indicates that risk reduction strategies focused on patients harboring germ-line BRCA1 mutations are effective." (PMID 27259235, 2016). "We reasoned that this was possibly due to the fact that mutant BRCA1/2 carriers exhibit dysfunctional HR pathway at the onset of carcinogenesis, whereas sporadic cancers may have somatic mutations to develop cancer." (PMID 27788678, 2016).
cancer (continued). "Nor were there any differences between respondents’ and non‐respondents’ main characteristics (age; gender; BRCA1/2 mutation status; living with a partner; offspring; educational level; depressive symptoms; cancer risk perception; and the type of document received)." (PMID 26205609, 2016). "The BRCA1 defective cancer cells show minimal level of HR or they are HR deficient." (PMID 27220670, 2016). "As the HMMR and AURKA-TPX2-TUBG1 gene products are functionally related in the regulation of mammary epithelial polarization, the associations between variants at these loci that were included on the iCOGS array and cancer risk in BRCA1/2 mutation carriers were assessed." (PMID 25830658, 2015). "Such modification could increase the risk of developing cancer, especially in the group of persons affected by germline mutation in BRCA1 gene, which affects the DNA repair." (PMID 25591549, 2015). "It is possible to imagine that phenotype specificities could be linked with an increased risk of unusual cancers in BRCA1 mutated patients." (PMID 25880076, 2015). "Our findings reveal mechanistically how BRCA1 controls repair pathway choice and may provide a novel diagnosis marker for cancer patients with a BRCA1 mutation." (PMID 27462418, 2015). "Whether Rif1 mutations also account for therapy resistance in BRCA1 mutant cancers remains to be tested." (PMID 25852742, 2015). "Large studies are required to verify whether complete loss of function BRCA1 mutations or interactions with other genes could be specifically associated with increased risk of rare cancers." (PMID 25880076, 2015). "Notably, truncating BRCA1 mutations lead to a higher level of sensitivity to ionizing radiation and genomic instability, as compared to other cancer associated BRCA1 missense mutations." (PMID 26246475, 2015). "Importantly, the cancer-predisposing C61G mutation in BRCA1, which abrogates its E3 ubiquitin ligase activity, and disrupts the BRCA1 RING domain and its interaction with BARD1, did not significantly alter the frequency of fusions induced by TRF2 depletion." (PMID 25582120, 2015). "We note that these PPVs were previously deemed benign with clinical testing (Myriad Genetics) in patients for whom their cancer could have been associated with BRCA1/2 mutations." (PMID 26023681, 2015). "We envision that 53BP1 hypo-phosphorylation and ATM inactivation, along with the failure of RIF1 and PTIP foci formation, may emerge as novel indicators for PARPi resistance in BRCA1-mutated cancer patients." (PMID 27462418, 2015). "Genetic or epigenetic inactivation of MCM8-9 is a new mechanism by which cancers can blunt the HR repair pathway, and as in cancers with mutations in BRCA1 or BRCA2, cancers that inactivate MCM8-9 are susceptible to chemotherapy agents that target cells with blunted HR." (PMID 26215093, 2015). "Cancer risk may be further increased in the context of BRCA1 mutations, which suppress DNA repair mechanisms." (PMID 26053551, 2015). "Furthermore, interactions have been established between mutation carrier status of BRCA1/2 genes and first-degree family history of cancer." (PMID 26236408, 2015). "The aim of this study was to determine whether SNPs reported to be associated with cancer risk in BRCA1 mutation carriers in other populations had the same association in the Norwegian population." (PMID 26052370, 2015).
cancer (continued). "As BRCA1 is involved in multiple cellular processes, it is likely that deleterious mutations are not all equivalent, and therefore would have varying relative risks for cancer development." (PMID 26246475, 2015). "Identifying a deleterious BRCA1/2 variant in a patient can also be helpful to family members, who may need access to genetic counseling and testing to assess their cancer risk and identify appropriate management." (PMID 26295337, 2015). "TdT, as other members of the X family of polymerase (pol λ and pol μ), contains breast cancer susceptibility protein BRCA1 C-terminal (BRCT) domain in their N-termini to mediate protein/protein and protein/DNA interactions in DNA repair and cell cycle checkpoint pathways." (PMID 26053431, 2015). "A pioneering breakthrough in SL-based cancer therapy showed that inhibition of poly (ADP-ribose) polymerase (PARP) in cancer cells that harbour loss-of-function events in the breast-cancer susceptibility genes BRCA1 and BRCA2 is dramatically lethal to these cells." (PMID 26427375, 2015). "BRCA1 is involved in the differentiation of breast epithelial cells, and its mutation impairs luminal progenitor cell differentiation and converts ER-positive luminal tumors into basal-like cancer." (PMID 25992773, 2015). "PARP inhibitor can selectively kill BRCA1-deficient and HR-repair deficient cancer cells." (PMID 25769025, 2015). "A third complicating factor in developing PARP inhibitors for HR-deficient cancers, is the recent observation that secondary mutations may dramatically alter the HR defect of BRCA1/2 mutation cancers." (PMID 25852742, 2015). "Besides selecting BRCA1/2 mutant tumors, also mutation of other HR genes results in cancers with similar characteristics, including PALB2 or RAD51C." (PMID 25852742, 2015). "Finally, TRβ positivity predicted a higher 5-year survival rate in metastasized (TRβ: p = 0.036) or lymph node positive (TRβ: p = 0.031) BRCA1 mutated cancer." (PMID 26029931, 2015). "Therefore, WGS identified additional predicted cancer risk mutations in BRCA1/2-carrier patients that were missed using standard clinical methods." (PMID 26023681, 2015). "As mutations in BRCA1 and BRCA2 may predict response to PARP inhibition regardless of cancer type, clinical trials testing the efficacy of PARP inhibitors in cancer with BRCA1 or BRCA2 mutations may need to be extended to all disease types, including HCC." (PMID 26449224, 2015). "We suggested earlier that the BRCA1 mutation carrier state in humans, in spite of its association with increased cancer risk, might confer some phenotypic advantages such as reduced predisposition to bone fractures due to increased estrogen exposure." (PMID 26488398, 2015). "In addition, Patient N acquired a homozygous deleterious somatic mutation in BRCA1 (Frameshift in exon 17, rs80357572) (36 out of 43 reads carried mutation), and the ultramutated carcinoma (Patient D) acquired a VUS in BRCA1 (T231N)." (PMID 25916844, 2015). "Specific deregulated miRNAs in BRCA1/2-associated carcinomas appear to target similar pathways." (PMID 26378051, 2015). "We addressed the question whether the patient with constitutive BRCA1 mutation diagnosed with HER2-positive carcinoma at young age have developed a carcinoma driven by BRCA1." (PMID 26426992, 2015). "DNA damage repair genes JWA, XRCC1 and BRCA1 were associated with clinical outcomes and could convert the response to the cisplatin-based therapy in some carcinomas." (PMID 25925371, 2015). "In the present study, we used a tagging SNP approach to evaluate whether the common genetic variation in the genes involved in the BER pathway could be associated with cancer risk in a large series of BRCA1/2 mutation carriers using a two-stage approach." (PMID 24698998, 2014). "Notably, several studies have documented that cancer cells expressing BRCA1 mutation and defective DNA damage repair through HR demonstrate synthetic lethality with PARP inhibition." (PMID 25026298, 2014).
cancer (continued). "Indeed, in premenopausal patients with BRCA1/2 mutations, removal of both ovaries and of the fallopian tubes reduces the risk of these cancers." (PMID 25429284, 2014). "However, in the patients exhibiting advanced stage (III–IV) cancer, BRCA1 methylation was significantly associated with improved OS (P=0.005) and DFS (P=0.007)." (PMID 24944674, 2014). "The influence of genetic factors may contribute to the poor prognosis, but familial history of cancer explains only 10%–37% of the cases, of which 10%–25% were attributable to BRCA1/2 mutations, which are currently known as the 2 major BC predisposing genes." (PMID 25006670, 2014). "Our results suggest that glycosylases involved in the first steps of the BER pathway may be cancer risk modifiers in BRCA1/2 mutation carriers and should be more comprehensively studied." (PMID 24698998, 2014). "Finally, the Israeli study involved practically exclusively BRCA1/2 founder mutations associated with cancer risk in Ashkenazi Jewish populations and, therefore, was by definition different from BRCA1/2 mutations in Austrian populations." (PMID 25036526, 2014). "BRCA1 plays important roles in protecting genome from aberrant DNA lesions, and mutations or deletion in this gene lead to genome instability and increased incidence of breast, ovarian and other cancers." (PMID 25216266, 2014). "This study aimed to determine whether telomere length (TL) is a marker of cancer risk or genetic status amongst two cohorts of BRCA1 and BRCA2 mutation carriers and controls." (PMID 24489760, 2014). "As a result of the BRCA1/2-related deficiency in HR, pre-cancerous cells within at-risk organs are unable to reliably repair DNA double-strand breaks, resulting in genomic instability that eventually leads to cancer." (PMID 25093514, 2014). "Additionally, we have found a significant association between the incidence of cancer in the family of those subjects and the presence of BRCA1 promoter methylation in their WBC (10/13) 77% (p = 0.036)." (PMID 25403427, 2014). "Therefore it is still unclear which of the known functions of BRCA1 are directly involved in tumor suppression and this further complicates the accurate assessment of cancer risk for BRCA1 VUS." (PMID 24695549, 2014). "We hypothesize that SNPs in PARP1 and other members of BER may be associated with cancer risk in BRCA1 and BRCA2 mutation carriers." (PMID 24698998, 2014). "In cancer cells, damage to the BRCA1 gene by the ruthenium-based drugs could lead to a loss of its functions and ultimately result in the death of the cancer cell." (PMID 24507701, 2014). "DNA glycosylases involved in the first steps of the BER pathway may be associated with cancer risk in BRCA1/2 mutation carriers and should be more comprehensively studied." (PMID 24698998, 2014). "A missense variant I157T affects the forkhead-associated (FHA) domain, where it mediates ATM-dependent CHEK2 phosphorylation and targeting of CHEK2 to bind partners such as BRCA1 and is associated with reduced DNA repair ability and increased risk for various cancers." (PMID 25431674, 2014). "There is only one study from the CIMBA consortium which has evaluated the role of three of the most studied SNPs in the XRCC1 gene, c.-77C>T (rs3213245) p.Arg280His (rs25489) and p.Gln399Arg (rs25487), ruling out associations of these variants with cancer risk in BRCA1 and BRCA2 mutation carriers." (PMID 24698998, 2014). "BRCA1-related tumorigenesis may be mainly caused by increased DNA damage and decreased genome stability that is a major hallmark of cancer." (PMID 25426449, 2014). "We propose that the new natural agents may have the potential of reducing cancer risk by the elimination of BRCA1 or BRCA2 homozygous mutated cancers." (PMID 24317580, 2014). "BRCA1 regulates ER expression positively, hence loss of BRCA1 can lead to ER-negative phenotype providing a molecular basis for the loss of ER expression in the majority of BRCA1 mutant cancers." (PMID 25364741, 2014).
cancer (continued). "TL was compared in BRCA1/2 mutation carriers with cancer and unaffected BRCA1/2 mutation carriers." (PMID 24489760, 2014). "This may be exacerbated by the additional cancer-driving effects of homozygous BRCA1 loss in the late stages of carcinogesis contributing to the overall aggressiveness of BRCA1-dependent tumours." (PMID 24950059, 2014). "First, we developed a mathematical model of BRCA-associated cancer progression, in which two types of mutations were included: (i) those conferring functional BRCA1/2 inactivation and (ii) those accelerating cell growth by inactivation of cell cycle regulation." (PMID 25158060, 2014). "Whether XIST interacts with BRCA1 to regulate cancer progression or if genetic instability due to loss of BRCA1 expression is responsible for reduced XIST expression is yet to be clarified." (PMID 25400658, 2014). "Loss of BRCA1 expression is also associated with an increased risk of several types if cancer." (PMID 25460500, 2014). "Indeed, BRCA1 mutated cancers are particularly sensitive to genotoxic and oxidative agents including PARP inhibitors and chemotherapeutics." (PMID 24704793, 2014). "Weighted and unweighted Cox regressions and linear regression analyses were used to assess whether TL was associated with BRCA1/2 mutation status or cancer risk." (PMID 24489760, 2014). "Women aged 18–24 who pursue BRCA1/2 mutation testing may receive highly personal and emotionally-charged cancer risk information before they are able to confidently manage this risk." (PMID 24586286, 2014). "On the other hand, increasing cellular ROS production may be utilized to treat BRCA1-associated cancers." (PMID 24704793, 2014). "The BRCA1 c.190T>C mutation was firstly described in a large Polish cancer family." (PMID 24516540, 2014). "Cancer cells in tissues of BRCA1 or BRCA2 mutation carriers are usually near tetraploid/polyploidy." (PMID 24775809, 2014). "There are data indicating that tumors developing in patients with hereditary BRCA1 mutation respond better to DNA-damaging cytostatics than sporadic cancers, and thus BRCA1 testing may be important for therapeutic decisions [e.g., Ref." (PMID 24478986, 2014). "TN and BLC again form a subtype of cancers which harbour the carriers for BRCA-1 mutation." (PMID 24964871, 2014). "Variants in BRCA1 that lead to functional inactivation, either by compromising gene expression, correct splicing, or protein structure and stability are associated with an increased risk for cancer." (PMID 24845084, 2014). "A reasonable explanation for this discrepancy was the relatively close relationship between family history and genetic susceptibility; patients who carry a mutation in BRCA-1 or BRCA-2 may be associated with an increased risk of bilateral carcinoma." (PMID 24736632, 2014). "Recent in vitro studies showing increased sensitization of cancers with defects in DNA homologous recombination (as seen in BRCA1/2 deficient cancers), to PARP inhibition by targeting of PIK3CA suggest that PIK3CA/mTOR pathway interactions result in homologous recombination steady state." (PMID 23971979, 2013). "However, it can be repaired by several DSB repair genes such as BRCA1/2 in which mutations have been proven to contribute to high risk of cancer in women." (PMID 24040396, 2013). "It is well known that inactivation of the product of the breast cancer 1 (BRCA1) gene is linked to susceptibility to early-onset breast and ovarian cancer, and inactivating mutations in the gene confer high lifetime risk of cancer." (PMID 23826138, 2013). "A durable antitumor activity was found in cancer associated with the BRCA1 or BRCA2 mutation." (PMID 24063014, 2013).